RNU6-1273P (RNA, U6 small nuclear 1273, pseudogene)
Gene: Small nuclear RNA gene on chromosome 12 (51,037,499 to 51,037,602, forward strand). Ensembl gene ENSG00000199903.
Homologues: Orthologues: chimpanzee U6 (99% identical), macaque U6 (89% identical), guinea pig U6 (86% identical). Paralogues in human: RNU6-1060P (90% identical), RNU6-15P (90% identical), RNU6-19P (90% identical), RNU6-12P (89% identical), RNU6-13P (89% identical), RNU6-166P (89% identical), RNU6-26P (89% identical), RNU6-31P (89% identical), RNU6-32P (89% identical), RNU6-41P (89% identical), RNU6-536P (89% identical), RNU6-1 (88% identical), and 1287 more.